TPTEP1 (TPTE pseudogene 1)
Synonyms: psiTPTE22
Gene: Transcribed unprocessed pseudogene on chromosome 22 (16,637,040 to 16,638,740, forward strand). Ensembl gene ENSG00000100181.
Diseases named in the same sentence as TPTEP1 in open-access papers:
TPTEP1 is named in the same sentence as 21 diseases in open-access papers, as found by Europe PMC text mining. Sharing a sentence is not in itself a finding about the gene and the disease. The quoted sentences say what the papers report.
glioma (7 papers, 2021 to 2026). A benign or malignant brain and spinal cord tumor that arises from glial cells (astrocytes, oligodendrocytes, ependymal cells). "Both in vitro and in vivo tumor xenograft studies confirmed that TPTEP1 knockdown enhanced glioma cell stemness and radioresistance-associated gene expression, such as OCT4, aldehyde dehydrogenase 1 (ALDH1), and γ-H2AX (the γ phosphorylated form of the histone H2AX)." (PMID 41431719, 2026). "lncRNA transmembrane phosphatase with tensin homology pseudogene 1 (TPTEP1) has been demonstrated to act as a tumor suppressor in glioma cells, and the upregulation of TPTEP1 in glioma patients has shown an improvement in overall survival probability." (PMID 34202078, 2021). "TPTEP1 attenuates miR-106a-5p, and the depletion of miR-106a-5p leads to cell stemness and radioresistance in glioma cells." (PMID 34202078, 2021). "However, some elevated expression of LINC00312 in NPC, TPTEP1 in glioma, and NKILA in laryngeal carcinoma was found to be related to radiosensitivity." (PMID 36323697, 2022). "While in glioma, lncRNA TPTEP1 downregulated radioresistance through miR-106a-5p/P38 MAPK." (PMID 35600868, 2022). "Distinctively dysregulated lncRNAs in gliomas include LOC150622 and LINC00645 in glioblastoma, LOC100216479 in diffuse H3K27M glioma, FLJ41350 and FTX in medulloblastoma, TPTEP1 and LOC100144595 in astrocytoma, and LOC100216545, FAM66B, and LOC100499405 in oligodendroglioma." (PMID 37693314, 2023).
hepatocellular carcinoma (5 papers, 2020 to 2024). A malignant tumor that arises from hepatocytes. "According to previous studies, the lncRNA TPTEP1 can interact with miRNAs or proteins to participate in cell proliferation and migration in many cancers, such as hepatocellular cancer and non‐small cell lung cancer." (PMID 39422584, 2024). "TPTEP1 expression was shown to inhibit hepatocellular carcinoma progression and non-small cell lung cancer proliferation." (PMID 35205253, 2022). "Our recent study reported that long non-coding RNA TPTEP1 inhibits hepatocellular carcinoma progression by interacting and suppressing STAT3 phosphorylation." (PMID 32123532, 2020). "Transmembrane phosphatase with tensin homology pseudogene 1 (TPTEP1) is a novel lncRNA that has been previously unveiled to repress tumor progression in hepatocellular carcinoma by hindering Signal transducer and activator of transcription 3 (STAT3) phosphorylation." (PMID 33985519, 2021). "TPTEP1 is a lncRNA that has been previously recognized as a tumor suppressor in hepatocellular carcinoma, while miR-1303 has been revealed to be upregulated and accelerate tumor development in several human cancers, such as hepatocellular carcinoma, neuroblastoma and gastric cancer." (PMID 33985519, 2021). "Among these, TPTEP1 was reported to suppress diabetic retinopathy by reducing oxidative stress, inhibiting stemness and radio resistance, and it exhibited substantial antitumor effects in several cancers, including hepatocellular carcinoma (HCC) and non-small-cell lung cancer (NSCLC)." (PMID 38279317, 2024). "Previous studies have shown that the expression of the lncRNA TPTE pseudogene 1 (TPTEP1) is widely suppressed in various cancers and that TPTEP1 can inhibit the proliferation, invasion and migration of hepatocellular cancer and non‐small cell lung cancer cells." (PMID 39422584, 2024).
fibroids (2 papers, 2024 to 2025). "In contrast to the findings in malignant tumors, leiomyomas which are benign expressed higher levels of TPTEP1 and CA3-AS1." (PMID 38279317, 2024).
gastric cancer (2 papers, 2021 to 2025). A primary or metastatic malignant neoplasm involving the stomach. "Functionally, the TPTEP1/miR-548d-3p/KLF9/PER1 axis reduces gastric cancer cell migration and invasion, with KLF9 serving as the critical regulatory node that translates the long non-coding RNA TPTEP1’s tumor-suppressive effects into PER1-mediated anti-metastatic activity." (PMID 40860800, 2025).
liver cancer (1 paper, 2021). An epithelial or non-epithelial malignant neoplasm that arises from the liver. "Further analyses found that TPTEP1 inhibits IL-6-induced phosphorylation of STAT3, thereby inhibiting the transcriptional activity of STAT3 and increasing the sensitivity of liver cancer cells to cisplatin." (PMID 33390845, 2021).
ovarian carcinoma (1 paper, 2024). A malignant neoplasm originating from the surface ovarian epithelium. "The expression of the long noncoding RNA (lncRNA) TPTE pseudogene 1 (TPTEP1) is significantly downregulated in ovarian cancer (OC)." (PMID 39422584, 2024). "In this study, RT–qPCR, Western blotting, RNA pull‐down, mass spectrometry and RNA immunoprecipitation were used to explore the function and mechanism of the long noncoding RNA (long noncoding RNA) TPTEP1 in OC to identify a new therapeutic target for ovarian cancer (OC)." (PMID 39422584, 2024). "In conclusion, our study confirms the important role of TPTEP1 in ovarian cancer (OC) progression and suggests that TPTEP1 inhibits the PI3K/AKT signalling pathway by directly binding PTBP1, possibly indicating the molecular mechanism underlying its biological function." (PMID 39422584, 2024).
tumor (13 papers, 2020 to 2026). "Our findings demonstrated increased expression levels of DDIT4 and TPTEP1 in CRC were associated with more aggressive tumor behavior and more advanced stages of the disease." (PMID 34107956, 2021). "In this study, we uncovered for the first time that TPTEP1 was an anti-tumor lncRNA and that miR-1303 was a facilitator in AML." (PMID 33985519, 2021). "Furthermore, the results of EdU, colony formation, wound healing, Transwell, flow cytometry, tumour formation assays in nude mouse, as well as WB analysis, showed that the lncRNA TPTEP1 can inhibit the proliferation, invasion and migration and promote the apoptosis of OC cells." (PMID 39422584, 2024). "TPTEP1 suppresses the progression of HCC cells by affecting the IL-6/STAT3 signaling pathway, revealing its tumor-suppressive role in HCC chemotherapy." (PMID 40352941, 2025). "Predictions based on the ENSG00000203739/ENSG00000271646-miR-637-CYBRD1 and TPTEP1-miR-196a-5p-RUFY2 regulation axes indicated that the two proteins may act as an oncogene and tumor suppressor, respectively, in the development of GBM." (PMID 32211330, 2020). "We identified some mutation markers specific to tumor types, including some typical tumor‐related genes (e.g., TP63, ABCC1, ABCC5, and TFDP1 in ESCA) as well as numerous noncoding genes (e.g., NPSR1‐AS1 and AC079466.1 in HCC) and pseudogenes (e.g., SDHAP3 and TPTEP1 in LUAD)." (PMID 38010945, 2024). "As patients with G-CIMP subtype tumors in general have a better prognosis, low-expression of TPTEP1 in non-G-CIMP subtypes may be consistent with a role as a tumor suppressor gene." (PMID 32211330, 2020). "Based on the theory of ceRNA, we found potential ncRNA regulatory pathways involving an oncogene and a tumor suppressor, ENSG00000203739/ENSG00000271646-miR-637-CYBRD1 and TPTEP1-miR-196a-5p-RUFY2, and constructed a local PPI network which might contribute to proliferation and invasion of GBM." (PMID 32211330, 2020). "Overexpression of DDIT4 and TPTEP1 in CRC patients with metastasis and advanced stages as well as in colorectal CSC-enriched spheroids indicates that increased RNA expression of these markers may be useful indicators of more aggressive tumor behavior and further disease progression in CRC patients." (PMID 34107956, 2021).
cancer (6 papers, 2020 to 2024). A tumor composed of atypical neoplastic, often pleomorphic cells that invade other tissues. "Contrary to the lung and liver cancer studies, the expression of TPTEP1 showed an up-regulation pattern in our CRC tissues compared to the adjacent normal tissues." (PMID 34107956, 2021). "Moreover, we observed higher expression of TPTEP1 in colorectal CSC-enriched spheroids than HT-29 cancer cells." (PMID 34107956, 2021). "After detection of CSC features, the RNA expression levels of DDIT4, SULF1, TPTEP1 and miRNAs (miR-181d-5p and miR-148b-3p) were measured using RT‐qPCR in colorectal CSC-enriched spheroids and HT-29 cancer cells." (PMID 34107956, 2021). "The official symbol of ENSG00000100181 is TPTEP1, which is also known as psiTPTE22. psiTPTE22-HERV has been reported to be epigenetically silenced by DNA methylation in cancers of the kidney, liver, lung, and stomach." (PMID 32211330, 2020). "Moreover, we unveiled that TPTEP1 confined AML cell proliferation through inactivating JNK/c-JUN signaling, a well-known oncogenic pathway verified in a variety of cancers, including AML." (PMID 33985519, 2021). "We also highlight the prognostic value of HPN-AS1, TPTEP1, and LINC00623 in cancer outcomes." (PMID 33082888, 2020).
TPTEP1 also shares sentences with these, for which no sentence is quoted: non-small cell lung carcinoma (3 papers); acute myeloid leukemia (1); astrocytoma (1); colorectal cancer (1); diabetic retinopathy (1); glioblastoma (1); laryngeal carcinoma (1); lymph node metastasis (1); medulloblastoma (1); neuroblastoma (1); oligodendroglioma (1); osteosarcoma (1); pancreatic tumor (1).